NRP1 (neuropilin 1)
Diseases named in the same sentence as NRP1 in open-access papers (continued):
Sharing a sentence is not in itself a finding about the gene and the disease.
COVID-19 (121 papers, 2020 to 2025). A disease caused by infection with severe acute respiratory syndrome coronavirus 2. "NRP1 is also involved in immune function, which is particularly relevant given the exaggerated immune responses associated with severe COVID-19." (PMID 40806445, 2025). "MMP-2, MMP-7, MMP-8, and neuropilin-1 were positively correlated, aligning with prior findings of elevated MMPs in severe COVID-19, linked to tissue damage and repair." (PMID 40557167, 2025). "Our data show that the AA genotype of rs10080, a 3′-UTR variant within NRP1, is associated with clinical presentations of COVID-19 in African individuals compared with the AG + GG genotypes." (PMID 37761938, 2023). "Gene polymorphisms within the receptors/co-receptors of SARS-CoV-2, including NRP1 (rs10080), were reported to associate with variable COVID-19 outcomes across ethnicities." (PMID 38138098, 2023). "Polymorphisms within ACE2 (rs2285666), TMPRSS2 (rs12329760), CD147 (rs8259) and NRP1 (rs10080) have been shown to associate with COVID-19 severity." (PMID 37761938, 2023). "Recently, it was identified that the SARS-CoV-2 virus, the causative agent of the latest COVID-19 pandemic, also contains the CendR motif, which proposed NRP1 as its additional entry point into human cells." (PMID 35955539, 2022). "NRP-1 expression is highly linked to olfactory dysfunction and COVID-19 severity due to the involvement of CNS." (PMID 36009579, 2022). "In particular, neuropilin-1 seems to play an important role in the underlying mechanism linking COVID-19 and diabetic nephropathy." (PMID 34360529, 2021). "A total of 128 COVID-19-associated genes are coexpressed, which are positively associated with NRP1 and ACE2 both in KIRC and KIRP." (PMID 34698182, 2021). "Up-regulation of NRP-1 protein in diabetic kidney cells hint at its importance in a population at risk of severe COVID-19." (PMID 33395426, 2021). "Although neuropilin expression patterns were similar in COVID and non-COVID-associated death, we identified a trend toward increased NRP1 protein levels in myocardial capillary ECs and transcriptional upregulation in pulmonary vascular ECs in COVID-19, consistent with prior findings." (PMID 41159753, 2025). "The accumulation of amyloid-β may be associated with the cognitive symptoms associated with COVID-19 and suggests that NRP1 inhibitors or antiviral medications may serve as therapeutic tools to prevent these consequences." (PMID 40614201, 2025). "However, we identified COVID-19-associated syncytial macrophages with high phagocytic activity in the lung that were positive for NRP1 and CD68 by CODEX and IHC." (PMID 41159753, 2025). "While the precise identity and localization of the signal remain uncertain, B lymphocytes are known to be permissive to productive SARS-CoV-2 infection, and NRP1 expression provides a potential mechanism for the severe lymphopenia associated with poor outcomes in COVID-19 patients." (PMID 41159753, 2025). "A recent study showed that COVID-19 has been linked to an increase in neuropilin-1 expression." (PMID 37239234, 2023). "Severe acute respiratory syndrome coronavirus 2 (SARS-CoV-2), which causes coronavirus disease 2019 (COVID-19), utilizes the host receptor angiotensin-converting enzyme 2 (ACE2) and the auxiliary receptor Neuropilin-1 (NRP1) to enter host cells." (PMID 37515185, 2023). "Although we highlighted hACE2 as a binding partner of SARS-CoV-2, a number of studies presented different docking partners of the human host to SARS-CoV-2 infections, such as NRP1, L-SIGN(CLEC4M), DC-SIGN(CD209), and CD147(BSG)." (PMID 35816517, 2022). "Therefore, a high NRP-1 level indicates the underlying development of pulmonary micro-thrombosis in patients with severe COVID-19." (PMID 36009579, 2022). "Similarly, high NRP-1 serum level is linked with ED, oxidative stress, and the risk of pulmonary thrombosis in patients with severe COVID-19, suggesting a compensatory mechanism to overcome immuno-inflammatory disorders." (PMID 36009579, 2022).
COVID-19 (continued). "Furthermore, severe COVID-19 causes arterial damage, and the up-regulation of NRP-1 plays a crucial role in renal dysfunction." (PMID 35891209, 2022). "Indeed, the upregulated gene expression of NRP1 was found in respiratory and olfactory epithelial cells of patients with COVID-19, which is associated with prominent symptoms, especially pulmonary and neurological manifestations." (PMID 36408220, 2022). "Particularly, NRP-1 is implicated in neurological manifestations of COVID-19, as it is thought to enable SARS-CoV-2 to enter the central nervous system through the respiratory and olfactory epithelia—where NRP-1 is highly expressed—including those of the nasal cavity." (PMID 36680105, 2022). "We therefore hypothesized that patients with cardiac fibrosis might be at risk for severe COVID-19 progression owing to increased NRP-1 expression in the heart and lung." (PMID 34745111, 2021). "Evidence has shown that the second route of viral entry, mediated by NRP1, may play a more dominant role in the underlying pathophysiological mechanism of olfactory dysfunction (OD) in patients with COVID-19 than ACE2-mediated entry." (PMID 34206057, 2021). "We therefore hypothesized that increased cardiac fibrosis may predispose to severe progression of COVID-19 owing to increased NRP-1 expression in the heart enabling viral cell entry." (PMID 34745111, 2021). "High level of NRP1 in lung cancer tissues is associated with poor survival, making it a potential therapeutic target in COVID-19 patients with lung cancer, while high level of TMPRSS2 correlates with better prognosis, excluding the attempt of targeting TMPRSS2 in comorbidity." (PMID 34168096, 2021). "Knowing that coagulation is also modulated by NRP-1, we carefully suggest that a key component of the pathology in CNS may be associated with an imbalanced clotting response in patients with COVID-19." (PMID 34202613, 2021). "Interestingly, S protein may compete with physiological ligands for binding to NRP1 and cause some of the dysfunctions reported in COVID-19 patients such as loss of olfaction, analgesic effects, immune interference and modulations of signaling pathways." (PMID 37047226, 2023). "Thus, we speculated that NRP1 was a potential valuable biomarker in predicting susceptibility to SARS-CoV-2 infection and targeting NRP1 in treating COVID-19 patients might achieve ideal clinical results." (PMID 36338984, 2022). "Therefore, high AngII in COVID-19 might be the possible cause of low sNRP-1 with high membrane-bound NRP-1 activity (mNRP-1)." (PMID 36009579, 2022). "Furthermore, patients infected with SARS-CoV-2 are at a higher risk of increased blood clotting and since NRP1 modulates blood clotting, it may also play a role in the pathology of blood clotting in COVID-19 patients." (PMID 35215277, 2022). "The authors argued that variability in NRP1 expression by age, race and ethnicity, or sex may explain the differing levels of morbidity of infection and the inverse association between anosmia and COVID-19 severity." (PMID 36074464, 2022). "Two independent studies recently published in Science have demonstrated that Neuropilin-1 represents a crucial co-factor necessary for the entry of the severe acute respiratory syndrome coronavirus (SARS-CoV-2)—which causes the coronavirus disease 2019 (COVID-19)—in human cells." (PMID 33540664, 2021). "Given that the gene expression of ACE2 is upregulated in the brains of patients with AD and may be associated with the mortality rate from COVID-19 in the elderly, we hypothesize that NRP1, which codes for a newly recognized SARS-CoV-2 spike receptor, may be also increased in AD patients." (PMID 34745215, 2021). "In addition, recent studies have suggested that the transmembrane receptor neuropilin-1 may also be implicated in the neurotropism of COVID-19." (PMID 33198412, 2020).
COVID-19 (continued). "A statistically significant reduction in NRP-1 expression was observed in the COVID-19 group decidua (p < 0.001), including in RT-qPCR - positive samples (p = 0.001), regardless of comorbidities or underlying conditions." (PMID 41319265, 2025). "Examination of NRP1 RNA expression in cells extracted from bronchioalveolar lavage of individuals with severe COVID-19 revealed heightened levels in cells infected with SARS-CoV-2, as opposed to uninfected cells." (PMID 39908250, 2025). "NRP1 showed higher and more consistent expression in controls, while expression in COVID-19 patients, although reduced, remained detectable." (PMID 40722799, 2025). "Similar to the lung, macrophages and sinus histiocytes in the lymph nodes of COVID-19 autopsies were strongly positive for NRP1 and NRP2." (PMID 41159753, 2025). "KEGG analysis of all the proteins revealed involvement in pathways related to COVID-19, suggesting a potential relationship between G4 sequences in the NRP1 promoter and COVID-19." (PMID 38674009, 2024). "Overexpression of receptors, such as ACE2 due to IFN-I response or NRP-1 due to miR-148a downregulation, may create an action/reaction loop that enhances the infectious capacity of Omicron variants, explaining infectious breakthroughs in the days following anti-COVID-19 product administration." (PMID 38549864, 2024). "Despite the functional importance of NRP1 in COVID-19 pathogenesis, the molecular mechanisms governing its endogenous regulation remain largely elusive." (PMID 38674009, 2024). "SARS-CoV-2 binding to host CSRs (i.e., ACE2, NRP1) is an initial step in the pathogenesis of COVID-19." (PMID 38555403, 2024). "Future studies can compare the safety and efficacy of agents directly targeting NRP1 with our proposed drugs indirectly lowering NRP1 to help select appropriate therapeutic strategy for patients with COVID-19." (PMID 39512370, 2024). "In some cases, it would be essential to block NRP1, as in the case of the coronavirus-induced disease 2019 (COVID-19) triggered by the severe acute respiratory syndrome coronavirus 2 (SARS-CoV-2) which is the causative agent." (PMID 39358558, 2024). "However, the mechanisms underlying the regulation of NRP1 in COVID-19 etiology remain unknown." (PMID 38674009, 2024). "The higher expression levels of NRP1 in the SARS-CoV-20-infected cells of the olfactory epithelium imply a hematogenous spread—a potential route to stroke in COVID-19 patients." (PMID 38201429, 2024). "Given its involvement in the immune system, regulation of vascular permeability, tumor promotion and progression, the clinical impact of NRP-1 has been extensively studied in cancer, leukemia, autoimmune disease, liver pathologies, kidney injury, and COVID-19." (PMID 38791476, 2024). "While some of the COVID-19 associated genes such as ACE2, TMPRSS2, and NRP1 were expressed in multiple organs, we did not detect significant viral mRNA load by RT-qPCR in the other organs processed." (PMID 37830426, 2023). "The interaction between S-glycoprotein and NRP-1 has been identified as a potential COVID-19 treatment target." (PMID 36903540, 2023). "According to our results, ambroxol shows a high potency of treating COVID-19 along with its polypharmacological benefits such as mucociliary clearance ability, anti-inflammatory effect, and adequate NRP-1-targeting ability." (PMID 36651548, 2023). "Evidently, the violin plot-based analysis and the heatmap analysis showed significantly higher expression of BSG and NRP1 in ACE2-positive COVID-19-infected brain cells as compared to the control group." (PMID 37239234, 2023). "The expression on proximal tubular renal cells of the key players in cellular viral uptake, ACE2, TMPRSS2, and NRP1, seems to be the mechanism for the direct kidney injury seen in patients with COVID-19." (PMID 38255667, 2023). "As such, this study is the first to investigate the relationship between variants within the NRP1 and CD147 genes and COVID-19 severity." (PMID 37761938, 2023).
COVID-19 (continued). "SARS-CoV-2 was found in Neuropilin-1 (NRP-1) -positive OSNs of the OE, OB and olfactory tracts in COVID-19 patients, indicating the critical roles of NPR1 in virus entry of the OSNs and anosmia." (PMID 35759516, 2022). "NRP-1 expression, in the present study, was significantly correlated with serum creatinine and urea levels in severe COVID-19 patients but, in moderate cases, it was significantly correlated with serum urea level only." (PMID 35891209, 2022). "The overexpression of NRP1 in olfactory cells also makes it a strong candidate for the mechanism of anosmia, which is very common in COVID-19 patients." (PMID 35215277, 2022). "When comparing COVID-19 patients to healthy controls, the level of NRP-1 mRNA expression was found to be significantly higher in all severe and moderate COVID-19 patients." (PMID 36298501, 2022). "NRP-1 is considered an immune checkpoint for T-cell memory; its immunological role in COVID-19 is unquestionable." (PMID 36341356, 2022). "NRP-1 is implicated in several aspects of a SARS-CoV-2 infection, including possible spread through the olfactory bulb and into the central nervous system (CNS) and increased NRP-1 RNA expression in lungs of severe COVID-19." (PMID 36298501, 2022). "Our findings suggested that targeting NRP1 or TPCN2 with chemicals was a potential therapeutic strategy for COVID-19." (PMID 36314791, 2022). "In this article, we compared the expression level of NRP1 in different tissues and organs among both healthy people, COVID-19 patients and cancer patients." (PMID 36338984, 2022). "The present study detected a highly significant upsurge of ACE2 and NRP-1 mRNA expressions in COVID-19 patients." (PMID 35891270, 2022). "Human autopsies performed on the olfactory epithelium after COVID-19 provided pathological findings in which SARS-CoV-2-infected NRP1-positive cells were present in the nasal cavity." (PMID 35327455, 2022). "By contrast, the proportion of NRP1-expressing cells was decreased in most lung cell types in COVID-19 patients (ciliated cells, B cells, T cells, natural killer cells, macrophages/monocytes, and dendritic cells) compared to the healthy donors." (PMID 35458567, 2022). "Increased NRP-1 mRNA expression in the lungs of severe Coronavirus Disease 2019 (COVID-19) has been noticed." (PMID 35891270, 2022). "RNA-seq data revealed that the NRP1 expression level was significantly higher in lungs from COVID-19 patients than non-COVID-19 controls (p = 0.00067)." (PMID 36338984, 2022). "The interplay of NRP-1, VEGF-Rs, and VEGF-A in nerves and blood vessels makes the association between SFN developing after COVID-19 or COVID-19 vaccination and increased VEGF-A levels plausible, but further research is needed." (PMID 36557705, 2022). "It was discovered that insulin-producing pancreatic β-cells express ACE2 and TMPRSS2 at low levels, whereas NRP1 expression is high in patients with COVID-19." (PMID 35955539, 2022). "In this study, we demonstrated the landscape of NRP1 expression among different tissue types and did a pan-cancer analysis to figure out potential vulnerable people to COVID-19 using public databases." (PMID 36338984, 2022). "Their expressions were positively correlated with kidney and heart function biomarkers and ACE2 and NRP-1 mRNA expressions in moderate and severe COVID-19 patients." (PMID 35891270, 2022). "This was verified by the significant correlation between NRP-1 expression and serum creatinine and urea levels in severe COVID-19 patients." (PMID 36341356, 2022). "We further analyzed the relationship between NRP1 and immunity to interpret the immune disorders observed in severe cases of COVID-19." (PMID 36338984, 2022). "Our study found that the levels of NRP1 were higher in COVID-19 survivors compared with those in healthy controls." (PMID 35288537, 2022). "NRP1 expression landscape in healthy people, COVID-19 patients, and cancer patients at both bulk and single-cell RNA-seq level was also depicted." (PMID 36338984, 2022).
COVID-19 (continued). "This cellular surface receptor participates in various facets in SARS-CoV-2 infection, which include the spread into the olfactory bulb from where it can reach the central nervous system and enhance pulmonary expression of NRP-1 in cases of severe COVID-19." (PMID 35891209, 2022). "The net effects of PDGF, TGF-β, and HIF-α2 in COVID-19 patients with AIS are mainly mediated by the expression of NRP-1." (PMID 36009579, 2022). "Recently, a potential dysfunction of the NRP-1/VEGF-A complex in acute COVID-19 has begun to be unveiled." (PMID 36557705, 2022). "Involvement of NRP-1 in immune function is convincing, given the role of an exaggerated immune response in disease severity and deaths due to COVID-19." (PMID 35891270, 2022). "As a result, COVID-19 can be suppressed by retaining NF-κB in an inactive state and suppressing NRP-1 expression." (PMID 36298501, 2022). "Furthermore, the distribution of these two receptors may form a plausible explanation for the spectrum of smell loss, with mild and typically short-lived smell loss from ACE-2 invasion versus more longstanding smell loss via NRP1 mediated sensory neuronal damage, following COVID-19." (PMID 33632171, 2021). "RNA-seq data show that NRP1 level is slightly decreased in peripheral blood of ICU admitted COVID-19 patients, unaltered in lung, while TMPRSS2 level is significantly decreased in lung of COVID-19 patients." (PMID 34168096, 2021). "Prior studies had identified neuropilin-1 as a target of miR-24, and indeed, that neuropilin-1 is a necessary co-factor of SARS-CoV-2 infection and is associated with COVID-19-associated CBV events." (PMID 34564316, 2021). "Combining our analysis, NRP1 is a potential therapeutic target for treating comorbidity of COVID-19 and lung cancers." (PMID 34168096, 2021). "In myocardium of deceased COVID-19 patients, we detected an elevated level of NRP-1 mRNA and protein expression that correlated highly with TGF-β1 expression." (PMID 34745111, 2021). "Analysis of NRP-1 RNA expression in cells isolated from bronchioalveolar lavage of patients with severe Coronavirus Disease 2019 (COVID-19) showed elevated expression in SARS-CoV-2–positive cells, but not uninfected cells." (PMID 33395426, 2021). "NRP-1 is implicated in several aspects of a SARS-CoV-2 infection including possible spread through the olfactory bulb and into the central nervous system and increased NRP-1 RNA expression in lungs of severe Coronavirus Disease 2019 (COVID-19)." (PMID 33395426, 2021). "Combing the analysis in lung cancer and COVID-19, NRP1 is a potential therapeutic target for treating comorbidity of COVID-19 with lung cancers." (PMID 34168096, 2021). "The abundance of NRP1 in CNS makes it a candidate target to prevent CNS infection and disease manifestations of COVID-19." (PMID 34168096, 2021). "Accordingly, sIL1-RL1 and NRP-1 RNA levels were significantly increased in the left ventricular tissue of patients who had died from COVID-19 compared to controls (B respectively)." (PMID 34745111, 2021). "The abundant level of NRP1 in COVID-19 patients makes it likely to get good response to the targeting strategy in patients." (PMID 34168096, 2021). "An increased NRP1 can enhance the susceptibility of immune system dendritic cells (DCs) to SARS-CoV-2 and induce cytokine storm, which is related to high COVID-19 mortality." (PMID 34206057, 2021). "More research is needed to refine the current understanding of the potential role of NRP1 in DN and COVID-19." (PMID 34360529, 2021). "In the left ventricular myocardium and lungs of COVID-19 patients, we found increased neuropilin-1 (NRP-1) RNA levels, which correlated strongly with the prevalence of pulmonary SARS-CoV-2 nucleocapsid." (PMID 34745111, 2021). "We also confirmed this increased NRP-1 expression in the left ventricular tissue of COVID-19 patients by Western blotting." (PMID 34745111, 2021).